HK2 (hexokinase 2)
Diseases named in the same sentence as HK2 in open-access papers (continued):
Sharing a sentence is not in itself a finding about the gene and the disease.
tumor (continued). "Overexpression of HK2 in HCC cells has been shown to be associated with increased tumor cell survival and proliferation and resistance to the anticancer agent cisplatin." (PMID 28445971, 2017). "Accumulating evidence has revealed that elevated HK2 expression is associated with not only the development and progression of tumor, but also with an unfavorable prognosis." (PMID 27824926, 2016). "Our in vitro DNA damage results suggested that radiation selectively targeted tumor cells with HK2 loss, whereas TMZ induced DNA damage showed only a modest increase in HK2 KD cells compared to TMZ treated control cells." (PMID 27588472, 2016). "As observed in our other GBM tumor cells, loss of HK2 in GSC 8–18 cells lead to significant reduction in lactate levels and increased oxygen consumption (**p < 0.001)." (PMID 27588472, 2016). "HK2 loss diminished both in vivo tumor vasculature as well as growth within orthotopic intracranial xenograft models of GBMs, and the survival benefit was additive with radiation and TMZ." (PMID 27588472, 2016). "Our results suggest HK1 and HK2 as key enzymes for glucose metabolism associated with survival of tumor cells." (PMID 28105937, 2016). "Our study also suggests that high expression of HK2 is associated with large tumor size and advanced TNM stages, which indicates that high expression of HK2 in HCC represents high levels of malignancy." (PMID 27255554, 2016). "Tumor immunohistochemical staining for HK2 was significantly associated with tumor staining for CKA (odds ratio 6.1, 95% CI 2.95–12.65, p<0.0001)." (PMID 23071593, 2012). "The HR associated with tumor HK2-expression among patients with CKA-positive tumors was 2.82 (95% CI 1.30–7.03)." (PMID 23071593, 2012). "Differences in tumor HK2 expression were associated with tumor grade (p = 0.008) and cancer stage (p = 0.001), while CKA expression differed significantly only across cancer stage (p = 0.048)." (PMID 23071593, 2012). "Moderate to high intensity tumor staining for HK2 was also positively associated with mortality (HR 2.19, 95% CI 1.24–3.63)." (PMID 23071593, 2012). "The association of tumor HK2 expression with HCC grade, stage, and overall survival in the current study helps to explain the results of these clinical FDG PET studies, given that the cellular retention of FDG is mediated by HK2." (PMID 23071593, 2012). "Increased mortality was associated with tumor HK2 expression (p = 0.003) as well as CKA expression (p = 0.03) with hazard ratios of 1.86 (95% confidence interval (CI) 1.23–2.83) and 1.59 (95% CI 1.04–2.41), respectively." (PMID 23071593, 2012). "In other cancers, expression of HK2 has been strongly associated with increased tumor biologic aggressiveness." (PMID 23071593, 2012). "Tumor expression of HK2 differed significantly across tumor grade and cancer stage and was associated with poorer overall survival." (PMID 23071593, 2012). "Tumor HK2 expression was also associated with increased mortality (p = 0.003), with a median survival time of 28 months for 71 patients with HK2-positive tumors compared to 72 months for 86 patients with HK2-negative tumors." (PMID 23071593, 2012). "Furthermore, the HK2 K144 mutation markedly enhances tumor cell glycolysis, fostering increased proliferation and migration both in vitro and in vivo." (PMID 41688443, 2026). "Studies indicate that CRCs with high glucose metabolism often exhibit elevated standardized uptake values on PET scans, with concurrent upregulation of hexokinase 2 and lactate dehydrogenase A, which are closely associated with rapid tumor progression and poor prognosis." (PMID 41415548, 2025). "Cluster 1 contained genes significantly upregulated in AMPKα1/α2–deficient tumor-infiltrating Treg cells and included genes encoding chemokines (Ccl2, Ccl7, Ccl8), modulators of lipid metabolism (Cd36, Pparg, Lpl, Abca1), and glycolytic enzymes (Hk2, Hk3)." (PMID 40100289, 2025).
tumor (continued). "Following cryoablation, pHe values within the tumor shifted toward physiological neutrality, accompanied by histopathologic evidence of decreased expression of hexokinase-2 (HK2) and lysosome-associated membrane protein 2 (LAMP-2), indicating downregulation of glycolytic flux and lysosomal activity." (PMID 41377976, 2025). "Additionally, HK2 has been implicated in promoting immune evasion by enhancing PD-L1 expression on tumor cells, further dampening anti-tumor immune responses." (PMID 40181966, 2025). "In some tumor cells, HK2 expression activity is usually elevated, which is associated with rapid tumor growth with high metabolic demands, so some recent studies have focused on targeting HK2 to inhibit tumor growth by disrupting glucose metabolism and reducing the energy supply to the tumor." (PMID 40696413, 2025). "Hexokinase 2 (HK2) catalyses the initial phosphorylation of glucose to sustain glycolytic flux into cancer cells, while its overexpression enhances glycolytic flux, supporting drug resistance and tumour growth besides associated with poor prognosis." (PMID 41154605, 2025). "A number of tumour s with high expression of HK2 have been associated with malignant properties." (PMID 39713255, 2024). "Accordingly, HK2 may be related to lncRNA and co-regulated tumor pathogenesis and development, but the underlying mechanism needed to be further studied." (PMID 36072431, 2022). "In summary, this study demonstrated that tumor HK2 expression/glycolysis can influence the immune profile of the TME, and an increase in tumor HK2 expression/glycolysis might be linked to a decreased CD8 + T-cell to Treg ratio, implying a poor prognosis." (PMID 36320008, 2022). "Besides, K63-linked ubiquitination of Hexokinase 2 induced by HectH9 modulates its mitochondrial localization and function, which controls tumor metabolism and apoptosis." (PMID 36202787, 2022). "For glucose metabolism, tumor extract-stimulated bone marrow-derived macrophages, which mimic tumor-associated macrophages (TAMs), show an upregulated molecular signature of glycolysis, and its key enzyme, HK2, is elevated." (PMID 36115986, 2022). "We demonstrated that a higher HK2 expression which stands for higher rate of tumor glycolysis is associated with an immunosuppressive microenvironment characterized by a decrease in CD8 + T-cell infiltration relative to Treg infiltration in lung and colon cancers." (PMID 36320008, 2022). "The upregulation of HK2 in cancers is mainly associated with tumor progression and mortality." (PMID 35265223, 2022). "The tumor repressive role of miR-202 is linked to its ability to directly target 3'-UTR of HK2." (PMID 33442412, 2021). "CIBERSORT investigation indicated that HK2 expression had associated with tumor immune cell infiltration, including regulatory T cells (P = 0.004), resting NK cells (P = 0.018), M0 macrophages (P = 0.002), activated mast cells (P = 0.042) and resting mast cells (P = 0.025)." (PMID 34708035, 2021). "Notably, IL13Rα1-overexpressing PCa cells were more susceptible to apoptosis and exhibited reduced tumor growth after exposure to the HK2 inhibitor, 2-deoxy-D-glucose (P < 0.01)." (PMID 34652890, 2021). "The HK2 converts glucose into glucose 6-phosphate during the first rate limiting step of glycolysis, and its elevated expression has been implicated in promoting tumor growth and invasion as well as developing diabetic glomerulopathy." (PMID 33520443, 2021). "Besides its role in glucose anabolism, we sought to determine the effect of HK2 on tumor proliferation and the underlying mechanism." (PMID 32083006, 2020). "The HK2 pathway could be one of the causes of tumor relapse in DLBCL subtype of B lymphoma patients." (PMID 29335581, 2018). "The results of a recent study also suggest that HK2 expression might be closely associated with tumour metastasis." (PMID 27926482, 2017).
tumor (continued). "We hypothesized that the extended survival observed in our mice by inhibiting tumor glycolysis through HK2 loss may be a consequence of altered tumor neo-vascularization." (PMID 27588472, 2016). "Therefore, it is not surprising that proliferative state and the glycolysis associated genes GLUT1, HK1 and HK2 cannot alone explain the FDG uptake in the tumor tissue." (PMID 26824929, 2013). "The role of glycolysis in sustaining tumor progression may therefore underly the association between tumor HK2 expression and patient mortality observed in the current study." (PMID 23071593, 2012). "In this model, the HR associated with tumor HK2 expression was 1.62 (95% CI 1.00–2.60)." (PMID 23071593, 2012). "More and more evidence further supports the use of natural compounds such as paeonol, the active ingredient DT-13 of ophiopogon, and targeted inhibitors to enhance chemotherapy sensitivity and reduce tumor invasion of GC by disrupting HK2 and related pathways." (PMID 41171531, 2026). "In an MC38 syngeneic tumor model, baicalin significantly inhibited tumor growth, reduced HK2 protein levels, activated the cGAS/STING pathway, and promoted a shift in tumor-associated macrophages toward an M1-like polarization state." (PMID 42158859, 2026). "Licochalcone A (LicA) also demonstrates promise by downregulating HK2 expression through blockade of the Akt pathway, thereby impairing glucose utilization and delaying tumor progression." (PMID 41171531, 2026). "In trastuzumab-resistant GC, metformin suppresses HK2-dependent glycolysis by inhibiting period circadian regulator 1 (PER1)-mediated circadian regulation of HK2, thereby restoring trastuzumab sensitivity and inhibiting tumor growth." (PMID 41171531, 2026). "Studies have shown that HK2 inhibition reduces glucose uptake, decreases lactate production, and impairs tumor growth." (PMID 40243996, 2025). "In our study, we observed that FBZ regulated glycolysis in EMT6 cells through HK2 and induced pyroptosis in tumor cells." (PMID 40756987, 2025). "We subsequently performed IHC experiments on mouse tumour tissues and found that the intensity of SPARC, P‐STAT3, and HK2 staining was significantly greater in tumour tissues from the OE‐SPARC group than in those from the control group." (PMID 40415238, 2025). "HK2 acts as a dual mediator; as a rate-limiting glycolytic enzyme, it sustains tumor metabolism, as a caspase-3 interactor, it controls the initiation of pyroptosis." (PMID 41415273, 2025). "Hexokinase, specifically HK2, is a pivotal enzyme in glucose metabolism regulation and energy metabolism in tumor cells." (PMID 39870616, 2025). "3-Br PA enables to covalently modify to HK2 protein and directly triggers its dissociation from mitochondria, which attenuates glycolytic capacity and promotes the apoptosis and death of tumor cells due to an insufficient energy supply." (PMID 40612109, 2025). "Elevated HK2 expression correlates with larger tumour size, deeper invasion, liver metastasis, and advanced TNM stages in CRC patients." (PMID 41154605, 2025). "An in vivo study has confirmed that the cGAS-STING pathway can inhibit HK2 to restrict tumor aerobic glycolysis and promote antitumor immunity." (PMID 41373022, 2025). "This article summarizes the role of HK2 in regulating tumor metabolic reprogramming and presents advancements in anticancer research of certain natural HK2 inhibitors." (PMID 39991762, 2025). "Similarly, HK2 positivity was significantly reduced in treated tumors compared to untreated (1.56 ± 0.25 vs 5.24 ± 0.68; p = < 0.01), suggesting lower glycolytic activity, likely attributed to the loss of viable tumor cells within the cryoablation zone as evidenced by histological necrosis." (PMID 41377976, 2025). "As HK2 drives oncogenic functions and metabolic reprogramming in cancer cells to support growth and survival, targeting HK2 is a promising anti-tumor strategy." (PMID 40734168, 2025).
tumor (continued). "Compared to oxaliplatin, BrPt3 more effectively impaired the glycolytic capacity of tumor cells, as evidenced by significantly reduced levels of pyruvate, lactate, ATP, and HK2 enzyme expression." (PMID 40589471, 2025). "As the most active isoenzyme in the HK family, the activation of HK2 drives tumor metabolism toward glycolysis in various malignant tumors, thereby regulating tumor progression and chemoresistance." (PMID 40264038, 2025). "For instance, in gastric cancer, HK2-driven glycolysis is regulated by circadian rhythms, promoting tumor growth and contributing to Trastuzumab resistance." (PMID 40520908, 2025). "HK2 plays a pivotal role in cancer metabolism, particularly by driving metabolic reprogramming within the tumor microenvironment, thereby enhancing its oncogenic potential." (PMID 40520908, 2025). "With the overcoming of current challenges and more in-depth cell and animal model studies and even clinical studies, the targeted therapy of HK2 is expected to become an important strategy for tumor therapy, bringing more treatment options to patients." (PMID 39991762, 2025). "LND has been reported to inhibit the rate-limiting glycolytic enzyme HK2, thereby disrupting the energy supply required for tumor cell proliferation." (PMID 41150773, 2025). "In the M6A-dependent pathway, VIRMA regulates key oncogenes (e.g., FOXM1, HK2) and tumor suppressor genes (e.g., RND3, BTG2), affecting the proliferation, metastasis, metabolic reprogramming, and drug resistance of tumor cells." (PMID 40723784, 2025). "HK2 degraders cause mitochondrial damage and then induce GSDME-dependent pyroptosis and ICD, resulting in increased anti-tumor immunity." (PMID 41246345, 2025). "HK2 expression is increased in MYCN amplified tumours in Kocak and Cangelosi datasets when compared to MYCN non‐amplified tumours (****p < 0.0001)." (PMID 41420301, 2025). "As a glucose sensor and protein kinase, HK2 plays an important role in the regulation of tumor immune escape." (PMID 39991762, 2025). "Ultimately, our findings demonstrate that the expression of HK2 significantly enhances anti-tumor function both in vitro and, importantly, in a xenograft model of human tumors." (PMID 40181966, 2025). "The transcription factor Foxp1 plays a regulatory role in the HIF-1α-HK2 pathway, which can improve the high glycolysis of tumor ECs and limit tumor angiogenesis, thereby effectively slowing down tumor growth." (PMID 40141029, 2025). "In tumor vascular remodeling, pericyte-expressed hexokinase 2 (HK2) impairs vascular support by activating ROCK2-MLC2, while inhibition of HK2 activity improves vascular function and enhances the delivery of chemotherapy drugs." (PMID 40821116, 2025). "provided a proof of concept to eliminate tumour immune evasion for improved cancer treatment with combined HK2 inhibitors and immune checkpoint blockade therapies." (PMID 39754316, 2025). "The inhibition of HK2 has garnered significant attention in cancer research due to its critical role in tumor metabolism." (PMID 40243996, 2025). "Glycolysis inhibition by HK2 KD had similar effects on the tumor immune microenvironment as observed in KRAS inhibition by MRTX1133, including decreased macrophage infiltration and increased CD8+ T cell infiltration and activity." (PMID 39883522, 2025). "While HK1 transcript remained similar in both tissue types, HK2 expression was 35% lower in CRC tumours." (PMID 40045444, 2025). "The HK2 enzyme expression plays a crucial role in tumor progression through the connection between the increased glucose uptake by cancer cells and the aerobic glycolysis, also known as the Warburg effect." (PMID 39955067, 2025). "In this study, we have demonstrated the feasibility of genetically engineering T cells to overexpress HK2, a key and the first enzyme in the glycolysis pathway, to enhance their anti-tumor efficacy." (PMID 40181966, 2025).
tumor (continued). "HK2 is involved in the regulation of glycolytic pathways, and providing energy and biosynthetic substances for tumor growth and invasion." (PMID 39991762, 2025). "In the nude mouse model of subcutaneous tumor, the increase of HK2 mRNA was accompanied by the increase of lactic acid level." (PMID 39991762, 2025). "HK2 expression is increased in stage 4 tumours when compared to stage 1 tumours in Kocak and Cangelosi datasets (****p < 0.0001)." (PMID 41420301, 2025). "During early tumor development, oncogenic drivers like KRAS mutations increase the expression of glycolytic enzymes (HK2, PKM2) to induce the Warburg effect." (PMID 40725147, 2025). "A characteristic of tumor cells is their ability to perform glycolysis at a faster rate, with the transcription of the glycolysis rate-limiting enzyme, HK2, serving as a crucial step in this process." (PMID 40775462, 2025). "Meanwhile, LARS promoted tumor growth and raised the expression of LA (the product of glycolysis) and that of HK2, GLUT1, and HIF-1α, the key enzymes in glycolysis, which were reversed upon 2-DG treatment." (PMID 40775462, 2025). "Elevated HK2 expression is associated with poor prognosis in HCC patients, underscoring its critical role in tumor progression." (PMID 40862732, 2025). "A well-characterized HK2 inhibitor, 2-deoxy-D-glucose (2-DG), competitively inhibits HK2 by mimicking glucose, reducing glucose-6-phosphate (G6P) production and suppressing tumor growth in various preclinical models." (PMID 40734168, 2025). "Genetic deletion of HK2 significantly reduced tumor burden and average tumor size in mouse models of LC and BC." (PMID 41294748, 2025). "Several drugs have been discovered to modulate the glycolysis process in tumor cells by targeting HK2." (PMID 40756987, 2025). "For instance, tumor cells upregulate enzymes such as hexokinase 2 (HK2), which not only promotes glycolysis but also increases PD-L1 expression, thereby suppressing CD8+ T cell activity and facilitating immune evasion." (PMID 41007256, 2025). "For instance, 3-bromopyruvate and sodium citrate hinder tumor growth by targeting HK2 and phospho-PFK." (PMID 40436857, 2025). "Then, the protein expression levels of the autophagy markers, p62 and Beclin-1, and glycolysis markers, GLUT1 and HK2, in tumor tissue were determined." (PMID 40969279, 2025). "NcRNAs play a crucial role in modulating HK2-induced glycolysis, thereby promoting tumor chemoresistance." (PMID 40264038, 2025). "Specifically, GEN-27 and lonidamine inhibit tumor progression by targeting HK2, while Benserazide inhibit tumor progression by targeting PKM2." (PMID 40264038, 2025). "Among the hexokinase isozymes, HK2 is highly expressed in tumor samples and correlate with poor pathological outcome." (PMID 41361062, 2025). "Hexokinase 2 (HK2) is widely distributed in various tissues, particularly showing significantly elevated expression levels in tumor tissues." (PMID 39991762, 2025). "A variety of strategies targeting key glycolytic genes (such as GLUT1, HK2, PK, etc.)can induce tumor cell death or enhance anti-tumor immunity by reducing ATP production and triggering mitochondrial damage." (PMID 41246345, 2025). "The deletion of HK2 can inhibit tumor cell proliferation, altering tumor metabolism with few side effects." (PMID 40612109, 2025). "HK2 also promotes the accumulation of lactic acid, affects the acidity level of the tumor microenvironment, and slows down the immune effect." (PMID 39991762, 2025). "Dysregulation of oncogenes and tumor suppressors usually leads to changes in the expression level of HK2, which in turn affects the reprogramming of glucose metabolism and has an important impact on the survival and proliferation of cancer cells." (PMID 39991762, 2025). "The overexpression of PDK4 and miR-122 effectively reversed the effects of OA and overexpressing PDK4 on the protein expression levels of Beclin-1, p62, GLUT1, and HK2 in the tumor tissue, respectively (P<0.05)." (PMID 40969279, 2025).